ENSG00000212529
Synonyms: LOC124900201
Gene: Small nucleolar RNA gene on chromosome 5 (172,252,334 to 172,252,478, reverse strand). Ensembl gene ENSG00000212529.
Gene Ontology:
Biological process: RNA processing
Cellular component: nucleolus
Homologues: Paralogues in human: SNORA57 (73% identical).